USP6 (ubiquitin specific peptidase 6)
Diseases named in the same sentence as USP6 in open-access papers (continued):
Sharing a sentence is not in itself a finding about the gene and the disease.
Ewing sarcoma (continued). "Upon activation, NK cells secrete IFNγ, which feeds back on USP6-expressing Ewing sarcoma cells to synergistically induce CXCL9/CXCL10." (PMID 37615015, 2023). "USP6 remains the only cancer cell–intrinsic factor, to our knowledge, demonstrated to modulate the immune landscape in Ewing sarcoma." (PMID 37615015, 2023). "USP6 is a ubiquitin-specific protease that was identified as an oncogene in transfection experiments with Ewing sarcoma DNA two decades ago." (PMID 26198694, 2015). "USP6 exhibits tumor-suppressive functions in Ewing sarcoma by enhancing immune activation and chemokine production (such as CXCL10 and CCL5), which could counteract tumor growth." (PMID 40348771, 2025). "Notably, the expression of USP6 in Ewing’s sarcoma has been shown to facilitate NK cell invasion and activation, thereby enhancing their tumor cell-killing potential and underscoring the positive impact of NK cell infiltration in impeding tumor growth." (PMID 38915446, 2024). "The activation of NK cells in USP6-expressing Ewing sarcoma tumors in vivo prompted us to examine whether USP6 could directly stimulate cytolytic activity of murine NK cells in vitro." (PMID 37615015, 2023). "This work reveals how USP6 reprograms the Ewing sarcoma TME to enhance antitumor immunity, and may be exploited for future therapeutic benefit." (PMID 37615015, 2023). "We posit that in vivo, this feedforward loop creates a highly immunostimulatory, chemokine-rich TME, which leads to further recruitment and activation of not only NK cells, but also CD8+ T lymphocytes, macrophages, and DCs, as is seen in Ewing sarcoma patient samples with high USP6 expression." (PMID 37615015, 2023). "Remarkably, expression of USP6 in subcutaneous Ewing sarcoma xenografts induces systemic activation and maturation of NK cells, and induces an abscopal response in which growth of distal tumors is inhibited, coincident with increased infiltration and activation of NK cells." (PMID 37615015, 2023). "Furthermore, in cocultured primary mouse LAKs and Ewing sarcoma cells, USP6 promotes LAKs maturation (from CD27lowCD11blow to CD27highCD11blow)." (PMID 37615015, 2023). "In addition, USP6 sensitizes Ewing sarcoma cells to killing by NK cells by increasing surface expression of the TRAIL receptor, DR5." (PMID 37615015, 2023). "USP6 has also been shown to confer sensitivity to interferon-mediated apoptosis in Ewing sarcoma." (PMID 35091542, 2022). "Furthermore, USP6 also stimulates the secretion of immune-related chemokines, augmenting the infiltration and activation of NK cells and additional immunocytes, significantly impeding Ewing’s sarcoma progression." (PMID 38915446, 2024). "Furthermore, USP6-expressing Ewing sarcoma and NK cells participate in a paracrine immunostimulatory feedforward loop, wherein IFNγ secreted by activated NK cells feeds back on USP6/Ewing sarcoma cells to induce synergistic expression of chemokines CXCL9 and CXCL10." (PMID 37615015, 2023). "Thus, not only does USP6 enhance the cytolytic function of NK cells, but it may also enhance sensitivity of Ewing sarcoma cells to killing through TRAIL, as supported by our previous studies." (PMID 37615015, 2023). "This study provides novel insights into the immunomodulatory functions of USP6, the only cancer cell–intrinsic factor demonstrated to regulate the immune TME in Ewing sarcoma." (PMID 37615015, 2023). "On a final note, we posit that due to USP6’s ability to promote a hot TME and broad innate immune activation, it holds promise not only as a monotherapy for Ewing sarcoma, but also for other malignancies and in combination therapy." (PMID 37615015, 2023). "The ubiquitin-specific protease TRE17/USP6, an oncogene identified in Ewing sarcoma, is highly expressed in several cancers and locally aggressive tumor-like lesions." (PMID 35926707, 2022).
Ewing sarcoma (continued). "Furthermore, USP6 renders Ewing sarcoma cells hyperresponsive to IFNs, such that IFN response genes are synergistically induced by ectopic IFNγ in Ewing sarcoma cells expressing USP6." (PMID 37615015, 2023). "We previously demonstrated that USP6 inhibits growth of Ewing sarcoma tumors when xenografted into nude mice, but not NSG mice." (PMID 37615015, 2023). "Intracellular flow cytometry confirmed that the USP6/Ewing sarcoma cells, and not the NK-92, were the predominant source of CXCL10." (PMID 37615015, 2023). "Immunotherapy has not been successfully utilized in Ewing sarcoma, and our results underscore the great potential of USP6 for advancing novel approaches." (PMID 37615015, 2023). "They found that IFN-beta-induced TRAIL-mediated apoptosis was observed in USP6-positive but not USP6-negative Ewing sarcoma cells." (PMID 34381187, 2021). "By transfecting genomic DNA fragments from the Ewing sarcoma (ES) cell line IARC-EW1 into the mouse fibro-blast line NIH3T3, isolating transformants that triggered tumor growth, and xenografting into nude mice, USP6 was first discovered as a putative oncogene in 1992." (PMID 40348771, 2025).
osteosarcoma (7 papers, 2020 to 2025). A usually aggressive malignant bone-forming mesenchymal neoplasm, predominantly affecting adolescents and young adults. "Molecular confirmation by FISH can demonstrate USP6 rearrangements at 17p13.2—a defining hallmark of primary ABC that differentiates it from ABC-like changes in GCTs or osteosarcomas." (PMID 41263005, 2025). "For differential diagnosis, USP6-associated soft tissue tumors with bone metaplasia are extremely easily confounded with extraskeletal osteosarcoma, especially in MO cases." (PMID 36727055, 2022). "The presence of ABC-like features in osteosarcoma may obscure accurate diagnosis, but markers such as MDM2, CDK4, and the lack of USP6 rearrangement can provide critical diagnostic clues." (PMID 40926903, 2025). "Due to the large size of the tumor, osteosarcoma could not be excluded from the original diagnosis after the lesion recurrence, and the diagnosis of FO was finally confirmed by USP6 FISH test." (PMID 36727055, 2022).
Bone Tumors (6 papers, 2008 to 2025). "Dysregulation of USP6 has been implicated in a spectrum of diseases, including bone tumors, breast and colorectal cancers, cranial fasciitis, and neurological disorders such as memory dysfunction." (PMID 40348771, 2025). "The third transcript was linked to USP6, which, when upregulated, is considered an oncogene causing bone neoplasms, and downregulation of this gene in older gulls suggests an anticancer mechanism." (PMID 32821278, 2020). "According to the 2020 WHO Classification of Bone Tumors, rearrangements involving the USP6 gene on chromosome 17p13 are typically observed in primary ABCs." (PMID 40926903, 2025). "While the 2020 WHO classification of soft tissue and bone tumors and some recent researchers have suggested that rare ST-ABC, MO, and FOPD should be classified into the same subclass of USP6-associated tumors." (PMID 40348771, 2025). "USP1 and USP6 inhibit osteogenesis in osseous tumors have been shown in previous studies." (PMID 36859264, 2023).
breast carcinoma (4 papers, 2012 to 2025). "Using PCR and Sanger sequencing, we successfully validated the DASE predictions in this breast cancer-related network, which includes cancer causative genes ZNF331 and USP6, and breast cancer risk associated gene DMBT1." (PMID 23107584, 2012). "According to a recent study, USP6 also contributes to resistance to hormone treatment and chemotherapy by improving the invasion and migratory capacities of breast cancer." (PMID 40348771, 2025). "In a subpopulation of aggressive basal-like breast tumors, USP6 overexpression increases glycolysis in breast cancer cells and points to a metabolic vulnerability that can be targeted with certain treatment drugs." (PMID 40348771, 2025). "Somatic mutations in USP6 (p.V678A and p.R475Q) and in ZNF331 (p.G193E) have been reported in 1% of primary breast cancer and 2% of ovarian cancer, respectively." (PMID 23107584, 2012). "Research suggests that USP6 may facilitate breast cancer spread by stabilizing proteins like matrix metalloproteinases (MMPs) that increase cancer cellṣ’ ability to invade." (PMID 40348771, 2025). "We used the TCGA database to analyze the expression of USP family members, and found that USP2, USP6, USP44 and USP53 in breast cancer tissues were significantly down-regulated compared with those in normal breast tissues, among which the first three have been studied in this field." (PMID 39044157, 2024).
fibroma of (4 papers, 2023 to 2025). "Together, these findings indicated that FOSL1 rearrangements, detectable by immunohistochemistry or direct sequencing of the FOSL1 transcript, are a common feature in desmoplastic fibroblastoma and absent from fibroma of tendon sheath, including USP6 wild‐type cases." (PMID 36426824, 2023).
sarcoma (4 papers, 2021 to 2024). A usually aggressive malignant neoplasm of the soft tissue or bone. "In addition, USP6-associated soft tissue tumors with bone metaplasia need to be differentiated from other osteogenic sarcomas, such as malignant peripheral nerve sheath tumors with heterogeneous bone differentiation and dedifferentiated liposarcomas with heterogeneous bone differentiation." (PMID 36727055, 2022). "Analysis of primary tumor samples have identified high expression of USP6 mainly in mesenchymal cancer including sarcomas." (PMID 34316327, 2021).
soft tissue tumors (4 papers, 2019 to 2025). "The most common soft tissue tumors associated with USP6 and bone metaplasia include FO, FOPD, MO, and ST-ABC." (PMID 40348771, 2025). "At present, soft tissue tumors in osteoid tissues have been successively confirmed to be USP6-associated tumors." (PMID 36727055, 2022). "USP6-associated soft tissue tumors with bone metaplasia predominantly consist of MO, FOPD, ST-ABC and FO." (PMID 36727055, 2022). "In our cohort, there were 73 cases of USP6-associated soft tissue tumors with bone metaplasia, including 44 MOs, 15 FOPDs, 2 ST-ABCs and 12 FOs." (PMID 36727055, 2022). "USP6-associated soft tissue tumors with bone metaplasia are a subgroup of myofibroblasts/fibroblastic proliferative lesions with metaplastic osteoid components, mainly including MO, FOPD, ST-ABC and FO." (PMID 36727055, 2022). "In summary, USP6-associated soft tissue tumors with bone metaplasia include MO, FOPD, ST-ABC and FO." (PMID 36727055, 2022). "In addition, it emphasizes the significance of molecular pathology in pediatric soft tissue neoplasms and improves diagnostic techniques while placing CF into the larger framework of USP6-associated tumors." (PMID 40348771, 2025). "This study will focus on USP6-associated soft tissue tumors with bone metaplasia." (PMID 36727055, 2022). "Genetic findings of USP6-associated soft tissue tumors with bone metaplasia." (PMID 36727055, 2022). "USP6-associated soft tissue tumors with bone metaplasia are benign lesions." (PMID 36727055, 2022). "However, MO-like zonal deposition pattern was observed in 50% of FO cases in our group, which indicated that there was evident histological overlap between FO and the other three subtypes of USP6-associated soft tissue tumors with bone metaplasia." (PMID 36727055, 2022). "In addition to those malignant tumors, USP6-associated soft tissue tumors with bone metaplasia should also be differentiated from some benign lesions, including proliferative fasciitis/proliferative myositis, bizarre parosteal ostochondromatous proliferation (Nora’s lesion) and subungual exostosis." (PMID 36727055, 2022). "More importantly, consistent MDM2 and/or CDK4 amplification is present in dedifferentiated liposarcomas, which is absent in USP6-associated soft tissue tumors with bone metaplasia." (PMID 36727055, 2022). "USP6 has also been demonstrated to regulate the stability of the c-Jun transcription factor, and high USP6 protein expression has been observed in bone and soft-tissue tumours." (PMID 30851349, 2019). "Another point we should address is that MYH9::USP6 was first identified in MO, and the novel USP6 fusion partners UBE2G1 and SNHG3 were uncovered in one case with MO and one case with FO, respectively, expanding our knowledge of USP6-associated soft tissue tumors with bone metaplasia." (PMID 36727055, 2022).
colon cancer (3 papers, 2022 to 2026). "Elevated expression of USP6 was directly linked to colon cancer invasion and metastasis." (PMID 40348771, 2025). "Both in vitro and in vivo colon cancer cell invasion and metastasis are facilitated by the Overexpression of USP6." (PMID 40348771, 2025). "It is thought that USP6 is a new gene that facilitates colon cancer invasion and metastasis." (PMID 40348771, 2025). "USP6 is substantially expressed in colon cancer tissues at the mRNA and protein levels." (PMID 40348771, 2025). "Additionally, a cell function study showed that USP6 could encourage the in vivo invasion of colon cancer cells and their liver metastases." (PMID 40348771, 2025). "USP32, USP1, USP37, USP12, and USP6 are elevated in macrophages, while USP32, USP9X, USP46, USP12, USP36, and USP24 are upregulated in classical monocytes of colon cancer relative to the control group." (PMID 41356798, 2026).
leukemia (3 papers, 2020 to 2023). A malignant (clonal) hematologic disorder, involving hematopoietic stem cells and characterized by the presence of primitive or atypical myeloid or lymphoid cells in the bone marrow and the blood. "The research sheds fresh information on the role of miR-146a-5p/USP6/GLS1 signaling in leukemia chemoresistance." (PMID 38260856, 2023). "The findings highlight the importance of miR-146a-5p/USP6/GLS1 signaling in chemoresistance of leukemia and provide new insights into therapeutic strategies for chemoresistant leukemia." (PMID 35091542, 2022). "The present study aimed to investigate the role of miR-146a-5p/USP6/GLS1 chemoresistance of leukemia cells and decipher the molecular pathways that were necessary for such effects." (PMID 35091542, 2022). "Leukemia cells’ apoptosis was dramatically reduced by USP6 overexpression in response to imatinib." (PMID 38260856, 2023). "USP6 overexpression significantly inhibited IM-induced apoptosis of leukemia cells." (PMID 35091542, 2022). "However, the role of miR-146a-5p/USP6/GLS1 in leukemia and chemoresistance of leukemia cells remains to be elucidated." (PMID 35091542, 2022).
spindle cell neoplasm (3 papers, 2020 to 2024). A benign or malignant neoplasm characterized by the presence of neoplastic spindle cells. "These USP6 rearrangements, present in approximately 92% of NF cases, have emerged as a reliable molecular marker that can distinguish NF from other spindle cell tumors." (PMID 39445266, 2024).
Asperger Syndrome (2 papers, 2019 to 2020). "Perturbation of USP6 expression through aberrant chromosomal translocation is associated with mental retardation and Asperger syndrome." (PMID 31841517, 2019). "Aberrant genetic disruption of the USP6 locus is also associated with social behavior disorders, such as Asperger syndrome." (PMID 31841517, 2019).
melanoma (2 papers, 2015 to 2020). A malignant, usually aggressive tumor composed of atypical, neoplastic melanocytes. "Interestingly, mutation of PTEN (phosphatase and tensin homolog), and expression of DUSP6 and USP6 (ubiquitin specific peptidase 6) are selected only for melanoma samples." (PMID 26274927, 2015).
Telangiectatic osteosarcoma (2 papers, 2022 to 2024). "Furthermore, the fact that USP6 rearrangement is generally absent in tumors with secondary ABCs and telangiectatic osteosarcoma is very useful because the differential diagnosis of these tumors and ABC has been problematic." (PMID 39850815, 2024).
uveal melanoma (2 papers, 2022 to 2025). A melanoma derived from melanocytes of the uveal tract. "Various USP6 inhibitors such as Momelotinib (CYT387), FT385, USP30 Inh-1, -2 and -3, 2,6-Diaminopyridine-3,5-bis(thiocyanate) (PR-619), and miR-130a were identified against tumor cancers, uveal melanoma, and osteosarcoma." (PMID 40348771, 2025).
biliary atresia (1 paper, 2020). A rare, biliary tract disease characterized by progressive obliterative cholangiopathy of the intra- and extrahepatic bile ducts, occurring in the embryonic/ perinatal period, leading to severe and persistent neonatal jaundice and acholic stool. "A recent study showed that ARF6 is involved in the EGFR pathway and is critical for proper bile duct formation, which suggests a non-superfluous role for USP6 in biliary atresia." (PMID 32848883, 2020).
colon adenocarcinoma (1 paper, 2025). "In the chemoresistance of colon adenocarcinoma (COAD), USP6 directly controlled the GOLPH3 protein’s deubiquitination and improved its stability." (PMID 40348771, 2025).
coronary artery disease (1 paper, 2019). "Besides Dendrin, only two proteins, junctional protein associated with coronary artery disease (JCAD) and USP6 N-terminal-like protein (USP6NL), contain two canonical ‘PPxY’ motifs separated by exactly two residues." (PMID 31486770, 2019).
fasciitis (1 paper, 2022). Inflammation process in fascia. "Meanwhile, USP6 encodes Ubiquitin-specific Peptidase 6, which is commonly associated with psuedosarcomatous fibromatosis and fasciitis." (PMID 35655140, 2022).
gastric cancer (1 paper, 2022). A primary or metastatic malignant neoplasm involving the stomach. "Ubiquitin-specific peptidase 6 N-terminal like (USP6NL, also called RN-tre or Tre2) has been implicated in some human malignancies, namely gastric cancer, colorectal carcinoma, and breast cancer." (PMID 35884836, 2022).
giant cell tumor (1 paper, 2022). A benign, intermediate, or malignant tumor that arises from the bone or soft tissue. "Although it is true that USP6 is positive in 70% of ABC cases, but not in giant cell tumors, it is also true that a USP6 negative tumor is still much more likely to be an ABC than a giant cell tumor, which is a very rare occurrence in the pediatric population." (PMID 35941207, 2022).
myeloma (1 paper, 2013). "Interestingly, the list includes the gene SLC31A2 a membrane pump involved in resistance to alkylating drugs; FBXW7, USP6, UBE2J1 and Wnt-5a involved in ubiquitin proteasome pathways known to affect myeloma biology." (PMID 24376673, 2013).
viral hepatitis (1 paper, 2020). An acute or chronic inflammation of the liver parenchyma caused by viruses. "Among the proteins encoded by these genes, ubiquitin carboxyl-terminal hydrolase 6 (USP6) regulates plasma membrane localization of ADP-ribosylation factor 6 (ARF6), while mucin 6, oligomeric mucus/gel-forming (MUC6) is involved in reactive biliary epithelium in viral hepatitis." (PMID 32848883, 2020).